ARID1A (AT-rich interaction domain 1A)
Diseases named in the same sentence as ARID1A in open-access papers (continued):
Sharing a sentence is not in itself a finding about the gene and the disease.
tumor (continued). "Therefore, we further investigated the pathology of this tumor by investigating how ARID1A, which is part of the same BAF complex as SMARCA4, changes in SAMRCA4 deficient tumors and examined the expression of SLC11A, a downstream factor of ARID1A." (PMID 35151345, 2022). "Therefore, ARID1A plays a context-dependent function in tumor inhibition and carcinogenesis in HCC." (PMID 36034939, 2022). "Previous reports have also described such immune contexture for ARID1A mutated tumours without specifying the heterozygosity, but whether this condition could be a biomarker of immunotherapy benefit in solid tumours is still debated in the literature." (PMID 36613564, 2022). "Conversely, the inactivation of ARID1A alone is not sufficient to cause tumour development." (PMID 35328379, 2022). "ARID1A inactivation may activate the cell cycle process, resulting in uncontrolled cell proliferation of cancer cells, indicating that ARID1A is a potential tumor suppressor function and the correlation between ARID1A deletion and tumorigenesis." (PMID 35421925, 2022). "Thus, a small molecule approach based on an HCC tumor cell line that has lost ARID1A through promoter DNA hypermethylation combined with a phenotypic differential screen for candidate ARID1A mimetics may be the better approach, by far." (PMID 36139547, 2022). "Furthermore, ARID1A alterations predict better outcomes after immune checkpoint blockade in pan-cancer analysis, independent of microsatellite instability or tumor mutational burden." (PMID 36077815, 2022). "Interestingly, the tumor-associated genes within the switched compartments were differentially expressed depending upon Arid1a depletion or not." (PMID 34689165, 2021). "ARID1A may function as a tumor-suppressor gene in pancreatic carcinogenesis, because its expression levels are associated with tumor differentiation and tumor stage, but not to lymph node metastasis, distant metastasis, sex, or age." (PMID 34671561, 2021). "As such, ARID1A mutant patients may derive additional benefits from treatments targeting TAMs to further enhance the response to immunotherapy by facilitating the access of CD8 cells into the vicinity of the tumour." (PMID 34359755, 2021). "As ARID1A is a tumor suppressor, the directly affected genes represent new entry points via which it may be possible to prevent or reverse malignant phenotypes resulting from inactivation of ARID1A." (PMID 34731603, 2021). "As for the expression loss of ARID1A, multiple studies had verified that the loss of ARID1A expression was also related to the alterations of genes belongs to PI3K/Akt signaling pathway and alternate the biological behaviors of tumor cells via this signaling pathway in variety of cancer types." (PMID 34715776, 2021). "In addition to ARID1A alteration, some other common contributors in cancer development, such as tumor microenvironment and tumor immunity, might also play roles in the pathomechanism of CCA, which should be further investigated." (PMID 34249744, 2021). "A recent pan-cancer analysis (not including OCCC) showed an increased mutational load in ARID1A-mutated tumours, suggesting that ARID1A mutant OCCCs may have a higher TMB, and thus potentially respond better to anti-PD-L1 therapies." (PMID 34359755, 2021). "In other words, full activation of YAP/TAZ requires not only nuclear accumulation of YAP/TAZ but also, as permissive step, overcoming the ARID1A-SWI/SNF barrier; the latter may occur by genetic-deletion of ARID1a or by the intrinsically altered physicality of the tumor microenvironment." (PMID 34782888, 2021).
tumor (continued). "Therefore, ARID1A, as an important tumor suppressor gene, may remarkably affect tumor occurrence and development." (PMID 33771191, 2021). "So far, it is not clear whether the effect of ARID1A on hormone signaling is related to tumor suppression, although ARID1A mutations are often present in cancers that occur in hormone-responsive tissues, such as the breast and the ovary." (PMID 34671561, 2021). "Moreover, we also found that ARID1A status was correlated with tumor size." (PMID 34805154, 2021). "Parallel evolution of five subclonal SMARCA4 mutations in this tumour with truncal ARID1A mutations suggests that SWI/SNF-complex aberrations are not only important for carcinogenesis but that progressive inactivation may contribute to cancer progression." (PMID 31949146, 2020). "This suggests that loss of ARID1A protein expression might not be as critical to tumor progression as to tumor initiation." (PMID 32334542, 2020). "NGS and IHC analyses of the tumor revealed multiple defects in DDR genes and proteins, specifically, heterozygous truncating mutations in CHK1, FANCM, RAD50, POLD1, and FANCP; compound heterozygous truncating mutations in ARID1A; and loss of ATM and ARID1A protein by IHC." (PMID 32568634, 2020). "In MSI-H tumours, alteration of ARID1A and other genes of the SWI/SNF complex could only be an epiphenomenon, since this tumour subtype already has many mutations due to its DNA repair defect, so that ARID1A alterations could only be passenger mutations without biological relevance of their own." (PMID 31906887, 2020). "Although recent advances have been made in Arid1a related to embryonic development, tissue repair, cell aging, apoptosis, and tumor formation, it remains unclear whether manipulating Arid1a is sufficient to enable axon regeneration or increase RGC survival following optic nerve injury in vivo." (PMID 32670021, 2020). "Second, although we obtained the novel finding that ARID1A mutations had a significant negative correlation with tumor aneuploidy levels, experimental validation could be necessary to confirm this finding from bioinformatic analysis." (PMID 31277418, 2019). "Therefore, in the context of KRAS mutations, ARID1A does not appear to function tumor suppressive, but rather facilitates the expression of genes particularly dependent on the MEK/ERK pathway." (PMID 31217031, 2019). "Interestingly, loss of ARID1A expression was observed in the lymph node metastasis but not in the primary tumour, suggesting a role of this alteration in tumour progression." (PMID 30641862, 2019). "ARID1B knockdown has been reported to destabilize the SWI/SNF complex and inhibit cell proliferation in both ARID1A-mutant cancer cell lines and primary tumor cells, suggesting that this protein could constitute an interesting therapeutic target for the treatment of ARID1A-mutant tumors." (PMID 31681423, 2019). "Patients with recurrent or metastatic disease who will be entering the growing number of clinical trials where a robust assessment of ARID1A protein expression in the tumour could be informative will require a test that is accurate and reproducible with a fast turn‐around time." (PMID 29659191, 2018). "This patient's tumor demonstrated 8 mutations overall including alterations in the PI3K, MAPK pathways (mutations in FBXW7, FGFR1) with concurrent epigenetic and transcriptional deregulation, specifically ARID1A, ETV1 rearrangement, NOTCH1 APIP-NOTCH1 fusion, and MYST3 amplification." (PMID 28781987, 2017).
tumor (continued). "However, we found ARID1A expression loss was correlated with poor OS in GC, irrespective of tumor clinical stage, tumor differentiation, MSI status, ARID1A deficiency rate and sample size." (PMID 27354232, 2016). "Finally, we demonstrate in xenografts of ccRCC how losses of PBRM1 and ARID1A impact tumor growth." (PMID 27764136, 2016). "Thus ARID1A knockdown seemed to have a more potent tumor-promoting effect than PBRM1 knockdown." (PMID 27764136, 2016). "Furthermore, ARID1A knockdown significantly increased HCC tumor growth and lung metastasis in vivo." (PMID 25975202, 2015). "However, inactivating mutations of ARID1A alone do not appear to be sufficient for tumor formation, but likely require additional genetic alterations resulting in activation of the PI3K-Akt pathway." (PMID 27231561, 2015). "In addition, we proved that ARID1A can inhibit tumor cell growth and colony formation in vitro." (PMID 22808142, 2012). "The data showed that the loss of ARID1A expression was significantly correlated with depth of tumor infiltration (T stage, P = 0.001) and tumor grade (P = 0.006), but not with age, gender, tumor size, distant metastasis (M stage), and tumor locus or local lymph node metastasis (N stage)." (PMID 22808142, 2012). "Collectively, ARID1A functions as a spatiotemporal HCC modulator, with microenvironmental cues determining its tumour‐suppressive or ‐promoting switch." (PMID 41578412, 2026). "This adds to our knowledge of the intricate involvement of ARID1A in the development of HCC and is in line with the function of tumour suppressor genes." (PMID 41578412, 2026). "We demonstrated the expression patterns of ARID1a/BAF250a and RIF1 in EOC, establishing their potential relevance in the context of tumor biology and malignant transformation." (PMID 42274628, 2026). "Specifically, among all the enriched targets, NF2, ARID1A, and TGFBR2 emerged as the top 3 enriched targets that were identified in more than half of the replicates, highlighting their substantial effect on tumor development." (PMID 41480763, 2026). "Drugs able to reactivate ARID1A and PTEN expression, by inhibiting PI3K/AKT and YAP signaling, are likely to suppress tumor growth and increase survival in TNBC patients." (PMID 41514650, 2025). "AT-rich interactive domain 1A (ARID1A), which is a key subunit of SWI/SNF complexes, demonstrates critical regulatory functions as a tumour suppressor gene in cancer." (PMID 40463905, 2025). "Furthermore, the tumor in our case also did not harbor alterations commonly reported in intracranial schwannomas, such as ARID1A/B, DDR1, or SOX10 mutations, suggesting that it might arise from a different mechanism than intracranial schwannomas." (PMID 40255822, 2025). "ARID1A, a subunit of the SWI/SNF chromatin-remodeling complex, functions as a tumor suppressor in various cancer types." (PMID 40369167, 2025). "Analysis of mRNA expression levels reveals a significant downregulation of ARID1A in TNBC compared to normal tissue, which is consistent with its tumor suppressor role." (PMID 40671262, 2025). "The authors further demonstrated that ARID1A expression is positively regulated by the HIPPO pathway, and as a result, it reinforces HIPPO signaling, forming a tumor-suppressive feedback loop." (PMID 40429787, 2025). "ARID1A, a key subunit of the SWI/SNF chromatin remodeling complex, plays a context-dependent function in cancer, acting both as a tumor suppressor and, in certain conditions, as an oncogene." (PMID 41514650, 2025). "ARID1A, a subunit of the SWI/SNF chromatin remodeling complex, has emerged as a pivotal tumor suppressor altered in a broad range of human malignancies." (PMID 40429787, 2025).
tumor (continued). "At the molecular level, ARID1A functions as the core subunit of the BAF chromatin remodeling complex, critically regulating the proliferative behavior of tumor cells." (PMID 41001036, 2025). "The interplay between ARID1A and the PI3K/AKT pathway plays a significant role in tumor development." (PMID 41514650, 2025). "We further analyzed tumor samples isolated from mice and observed that EMP treatment selectively inhibited tumor cell proliferation and induced apoptosis in HCT116 ARID1A−/− xenograft mice." (PMID 41360780, 2025). "ARID1A, which is a key subunit of SWI/SNF complexes, plays an essential role in preventing oncogene-driven tumorigenesis as a tumour suppressor gene." (PMID 40463905, 2025). "Conversely, when mice were fed with doxycycline (Dox) to induce ARID1A expression, the growth of ARID1A-overexpressed DMS273 xenografts was significantly suppressed, resulting in reduced tumor volume, weight, and size." (PMID 41049615, 2025). "Other members of the SWI/SNF complex, namely ARID1A/B and ARID2 are well-established tumor suppressor genes." (PMID 40514689, 2025). "This review will therefore focus specifically on PDAC, highlighting the significant, but less-understood roles of tumour suppressors, such as PTEN, KDM6A, and ARID1A in PDAC." (PMID 40723241, 2025). "To demonstrate the clinical relevance of these correlations, we evaluated the expression level of ARID1A, p-CHK1S345, ssDNA and tumor PD-L1 in CRC patients by immunohistochemical analysis." (PMID 40750787, 2025). "Specifically, we demonstrated its tumor‐promotive role and its downstream effects on SWI/SNF complex functioning through the negative regulation of ARID1A expression and the disruption of ARID1A‐bound BAF complex formation." (PMID 40671262, 2025). "ARID1B negatively regulates ARID1A, impairing SWI/SNF‐mediated tumor suppression and enhancing tumor survival." (PMID 40671262, 2025). "In early stages or under homeostatic conditions, ARID1A and ARID1B, when functioning properly within the BAF complex, contribute to the suppression of tumor progression by regulating gene expression through chromatin remodeling." (PMID 40671262, 2025). "ARID1A, a subunit of the SWI/SNF chromatin remodeling complex, is thought to play a significant role both in tumor suppression and tumor initiation, which is highly dependent upon context." (PMID 38835016, 2024). "Four candidate tumor suppressor genes RUNX3 (RUNX family transcription factor 3), ARID1A, ERRFI1 (ERBB receptor feedback inhibitor 1), and mTOR, are all located in the 1pter region and are involved in transcription and cell-cycle control." (PMID 39199659, 2024). "ARID1A is a core component of SWI/SNF chromatin-remodeling complex and contributes to tumor suppression." (PMID 39564571, 2024). "Mice with ARID1A-isogenic tumors on either flank were intraperitoneally injected with RITA and tumor volumes were periodically measured." (PMID 38811536, 2024). "Arid1a is a member of the canonical BAF (SWI/SNF) complex and a known tumor suppressor gene in other cancers." (PMID 39123453, 2024). "ARID1A is a subunit of the BAF chromatin remodeling complex that facilitates chromatin remodeling critical during development and serves as a tumor suppressor." (PMID 39766121, 2024).
tumor (continued). "ARID1A (AT-rich interaction domain 1A) is the largest subunit of the SWI/SNF (switch/sucrose non-fermentable) complex and plays an important role in chromatin remodelling and tumour suppression." (PMID 38893278, 2024). "ARID1A, a key subunit of the nuclear SWI/SNF protein complex, plays a crucial role in determining tumour identity by manipulating gene expression." (PMID 37173914, 2023). "This supports the idea that tumours lacking ARID1A may be more susceptible to immunotherapy." (PMID 38041544, 2023). "Candidate tumor-agnostic molecular targets in the three gynecological malignancies included ERBB2, PIK3CA, ARID1A, and KRAS." (PMID 38201563, 2023). "Defects in ARID1A (AT-rich interaction domain 1A), a component of the SWI/SNF chromatin remodeling complex, increase the sensitivity of tumor cells to ATR inhibitors." (PMID 37190157, 2023). "Our pilot study investigated the expression of ARID1A and the NOTCH receptors and WNT components CTNNB1 and FBXW7 in two OC cell cultures, then validated the results in gynaecologic tumour tissues." (PMID 36982928, 2023). "Therefore, HDAC6 inhibition selectively promoted apoptosis of cells with ARID1A mutation, but not ARID1A wildtype, as verified by the improved survival of ARID1A-deficient tumor-bearing mice upon treatment of a clinically applicable small molecule inhibitor of HDAC6." (PMID 36980292, 2023). "Our pilot study investigated mRNA expression of the SWI/SNF chromatin-remodelling complex gene ARID1A, NOTCH receptors, WNT pathway genes CTNNB1 and FBXW7 mRNA expression in two OC cell cultures as well as 51 gynaecologic tumour tissues." (PMID 36982928, 2023). "In a series of elegant in vitro and in vivo experiments, they show that ARID1A competes for YAP-binding with TEAD, providing essential tumor-suppressive function of the SWI/SNF complex." (PMID 37543677, 2023). "In the present study, the Hippo signalling pathway was found to be the top-ranked ARID1A-affected pathway, suggesting that ARID1A regulates EMT and tumour metastasis in TNBC by controlling the Hippo pathway." (PMID 37173914, 2023). "In other research, ARID1A was suggested to be a tumor suppressor in PCa, and to play a crucial role in MDSC recruitment, and the IKKβ/ARID1A/NF-kB feedback axis integrated inflammation and immunosuppression to promote PCa progression." (PMID 37569304, 2023). "Our data suggest that ARID1A competes with YAP by binding to it, thereby inhibiting the formation of TEAD/YAP complexes, and affecting tumour metastasis." (PMID 37173914, 2023). "Our study confirmed that ARID1A inhibits the formation of the YAP/TEAD complex, which subsequently inhibits tumour metastasis in vitro." (PMID 37173914, 2023). "Collectively, these results suggest that the anti-tumor function of PPARα involved not only SREBP1, but also p21/p27, antioxidant enzymes, and ARID1A." (PMID 37305395, 2023). "Our findings suggest that ARID1A protein transcriptionally modulates DUSP4 expression by remodeling chromatin, subsequently inactivating the MAPK pathway, leading to tumor suppression." (PMID 38071325, 2023). "We discovered that decreased ARID1A expression suppresses E‐cadherin expression, consequently loosening cell–cell junctions in COAD tissues and promoting tumour cell migration and invasion." (PMID 36420658, 2022). "Here, we show that ARID1A, a subunit of the SWI/SNF chromatin remodeling complex, functions downstream of inflammation-induced IKKβ activation to shape the immunosuppressive tumor microenvironment (TME)." (PMID 36435834, 2022). "In ARID1A-inactivated GBC, PD-L1 overexpression and impaired TIL function lead to immune evasion by the tumor and a worse prognosis." (PMID 35198440, 2022).